IL6 (interleukin 6)
Diseases named in the same sentence as IL6 in open-access papers (continued):
Sharing a sentence is not in itself a finding about the gene and the disease.
tumor (continued). "In addition, we found a modestly increased secretion of cytokines and chemokines (e.g., IL-6, TNF-α, MIP-1) by macrophages with the combination therapy compared with monotherapy, likely a result of their enhanced ADCP of tumor cells." (PMID 35167491, 2022). "In the peripheral tissues, the lack of tumor IL-6 at d 28 reduced Th17, and Th22 was also lowered." (PMID 36142210, 2022). "HCC is a well-known example of a tumor induced by inflammation, and a variety of immune and inflammatory factors, including T cells, cytokines, etc., play crucial roles in the development of HCC, including interleukin-6 (IL-6), interferon-α (TNF-α), TGF-β, and other cytokines." (PMID 36278230, 2022). "In addition to IL-6, HMC3 microglia also secreted detectable amounts of LIF and IL-11, suggesting that IL-6, LIF, and IL-11 may contribute to paracrine signaling in the MB tumor microenvironment." (PMID 35159191, 2022). "Indeed, both yeast extract and WGP attenuated tumor growth at the 4th week of the experiments, with the reduction in serum IL-1β and IL-6, but not TNF-α and IL-10, supporting a previous publication." (PMID 36142859, 2022). "In addition to IL-6, therapeutic agents targeting TGF-β signaling could interfere with the CAF activation or reduce the CAF numbers, leading to inhibited tumor growth and an anti-tumor effect." (PMID 35488263, 2022). "In nonsmall cell lung cancer, IL-6 upregulated PD-L1 expression through the JAK/STAT3 signaling pathway in vitro and increased the recruitment of MDSCs, M2 macrophages, and regulatory T cells (Tregs) while decreasing the infiltration of CD8+ T cells in tumor samples." (PMID 36497467, 2022). "On the other hand, anti‐mouse IL‐6R antibody given by i.p. injection twice a week from day 7 to day 21 after inoculation, did not inhibit tumor growth in the N‐inv model (rat IgG [control] vs. anti‐mouse IL‐6 antibody [mean ± SD], 0.865 ± 0.623 g vs. 1.561 ± 0.755 g; p = 0.173)." (PMID 35578571, 2022). "In vehicle-treated UM samples, a significant negative correlation was observed between IL-6 secretion and patient age, IL-13 secretion and tumour thickness, between VEGF-A secretion and largest ultrasound height (LUH), and between PlGF secretion and chromosome 8 alterations." (PMID 36698840, 2022). "It is well established that IL-6 is produced by tumor infiltrating macrophages and other myeloid cells in both IBC and non-IBC specimens and by other cells in the tumor microenvironment such as cancer-associated fibroblasts." (PMID 35565421, 2022). "Additionally, GSEA indicated that immune response-related pathways, such as inflammatory response and IL6–JAK–STAT3 signaling pathway, were significantly activated in CEBPB_High macrophages, which was consistent with the bulk tumor tissue analysis." (PMID 36353635, 2022). "Finally, tocilizumab will neutralize IL-6 signaling by antagonizing IL-6R regardless of the cellular source of IL-6 in the tumor microenvironment." (PMID 35260569, 2022). "Various cells in the TME, such as surviving tumor cells, damaged endothelial cells, tumor stromal cells, etc., can release numerous pro-inflammatory mediators, including arachidonic acid, cytokines such as MIP2 (CXCL2), IL6, IL- 1β, TNFα, complement system, etc.." (PMID 35645842, 2022). "However, IL6 was robustly induced only in the KDM5CHigh samples, and interestingly, it showed a significant positive correlation with NANOG only in this tumor subtype." (PMID 36142158, 2022). "The polysaccharides could activate macrophages, T-lymphocytes, B-lymphocytes, natural killer cells, and cytokines that are closely related to the killing of the tumor, such as tumor necrosis factor (TNF-α), interferon (IFN-γ), and interleukins (IL-2, IL-4, IL-6, and IL-12)." (PMID 35295918, 2022).
tumor (continued). "IL-6 may facilitate tumor metastasis via induction of glutathione release from hepatocytes and inter-organ transfer to metastatic foci, providing an experimentally testable connection between KLF9, IL-6, glutathione, and cancer dissemination in future studies." (PMID 35406507, 2022). "From this, we could postulate and form a model that IL-6 acts to promote CXCL13 and G-CSF production, which may act independently to aid 4T1 growth, and that G-CSF also promotes neutrophil expansion that supports 4T1 tumour growth." (PMID 35226704, 2022). "Interestingly, we observed an increased frequency of DCs in the tumor microenvironment of IL-6-/- mice, but not CD4+ T cells or CD8+ T cells at the time point assessed." (PMID 36405719, 2022). "Infiltration of Th17 in tumor microenvironment has been shown to promote tumor growth and angiogenesis, through induction of angiogenic factors (vascular endothelial growth factor/VEGF and prostaglandin E2/PGE2) and activation of oncogenic IL-6/Stat3 signaling." (PMID 36544761, 2022). "Moreover, many cytokines (e.g., TNF, IL-1, and IL-6) and VEGF produced as a result of neutrophil activation may increase tumor growth." (PMID 35165274, 2022). "In HBV-associated HCC, the level of IL-6 promoter methylation in males was higher than that in females, in those >50 years old than in those <50 years old, in HBV-DNA positive than in HBV-DNA negative, in tumor size>3 cm than in those<=3 cms." (PMID 35359408, 2022). "Thus, IL-6 induces the activation of its downstream cascade JAK2/STAT3 pathway, contributing to tumorigenesis by regulating cell cycle progression, angiogenesis and tumor cell escape of the immune system." (PMID 36591515, 2022). "IL-6 is produced by various types of lymphocytes and non-lymphocyte cells, such as T and B lymphocytes, fibroblasts, monocytes, mesangial cells, endothelial cells, keratinocytes, and several tumor cells." (PMID 36591515, 2022). "Indeed, IL-6 or IL-8 increased ATG5/12 conjugation and decreased p62, indicating cytokine-induced autophagy and, most importantly, autophagy inhibition suppressed tumor growth." (PMID 35884904, 2022). "EPA treatment inhibited the mRNA expression of inflammatory cytokines including IL-1β, IL-6, MCP-1, and TNF-α in both the CaOV3 and SKOV3ip tumors, which was validated by similar decreased levels of these inflammatory cytokines in the serum from mice of both tumor models." (PMID 35326656, 2022). "Functionally, TAMs support MM proliferation (by secreting IL6), angiogenesis (by secreting VEGF, CCLs, matrix metalloproteinases (MMPs)), and immunosuppression (by secreting IL10, TGFβ, indoleamine 2,3-dioxygenase (IDO) and inhibiting IL12 and TNFα production) in the tumor microenvironment." (PMID 36421358, 2022). "In the inflammatory tumor microenvironment (TME), innate immune cells such as monocytes and adaptive immune cells (e.g., T lymphocytes) directly contact or produce a variety of inflammatory mediators [e.g., tumor necrosis factor (TNF), IL-6] in response to aberrant signals from the tumor." (PMID 36313280, 2022). "Along with elevated IL-6 plasma concentration, we also demonstrated increased skeletal muscle lipid peroxidation (TBARS) and protein oxidation (AOPP) markers, combined with imbalanced skeletal muscle redox state, demonstrated by decreased GSH and GSSG ratio in tumor-bearing mice compared to control." (PMID 35847939, 2022). "Immune factors, including cytokines (such as interleukin-11 (IL-11), and interleukin-6 (IL-6)) and chemokines (including IL-6, CCL5, and CXCL10), play a role in converting normal fibroblasts into CAFs, and some of these immune factors act in a feedback loop between the CAFs and the tumor." (PMID 35300411, 2022). "Additionally, IL-6 secreted by MSCs could also signal through STAT3 to increase the number of colorectal initiating tumor cells and promote tumor formation." (PMID 35281017, 2022).
tumor (continued). "Besides, RuPOP@CM can enhance the activity of cellular immune response and produce inflammatory cytokines in blood including IL-6, IL-12 and TNF-α, which is of great significance in treatment for circulating tumor cells from tumor metastasis or hematologic tumors." (PMID 36064356, 2022). "Interestingly, the IL-6 signal loop on a self-sustaining IL-6/STAT3/AHR axis is one of the mechanisms that maintain the constitutive expression of the indoleamine 2,3-dioxygenase (IDO) enzyme in tumor cells." (PMID 36405719, 2022). "Irradiation-induced IL-6 and subsequent MDSC recruitment may enhance tumor regrowth." (PMID 36362050, 2022). "Therefore, the inhibition and regulation of IL-6/JAK2/STAT3 signaling pathway is conducive to the prevention and treatment of tumors and the improvement of prognosis, and it is also one of the important targets for screening anti-tumor drugs." (PMID 36591515, 2022). "TNF-α/IL-6 synergism has been reported to slightly advance TGF-β-mediated EMT, while IL-6 by itself can upregulate EMT markers like vimentin, whereas reducing the expression of E-cadherin via the JAK/STAT/Snail pathway, thus increasing the invasive potential of the tumor." (PMID 36077865, 2022). "For instance, NF-ĸB-mediated factors (TNF-α, IL-1β, IL-6, CCL2, CXCL8 and CXCL10) can protect against apoptosis, and pro-angiogenic growth factors (such as VEGF or PDGF, TGF-β and FGF) that adapt tissue architecture and support tumor cell migration, invasion and metastasis." (PMID 35707536, 2022). "Furthermore, cytokines such as GM‐CSF, macrophage colony‐stimulating factor (M‐CSF), IL‐6, IL‐10, IL‐1β, PGE2, and TGF‐β, whether secreted or produced by tumor‐derived exosomal vesicles, enter the bone marrow or circulation, and generate MDSCs." (PMID 35791509, 2022). "Investigating the effects of LKB1 on the tumor microenvironment, they found that its inactivation promoted greater expression of neutrophil-recruiting chemokines such as CXCL7 and CXCL5 and pro-inflammatory cytokines such as IL-6, which contributes to neutrophil accumulation in NSCLC models." (PMID 35646638, 2022). "Thus, combinatorial approaches through multispecific antibodies targeting multiple pathways might encourage redefining and reprogramming the TME to efficaciously eradicate tumours, and inhibiting TAM-derived IL-6-mediated signalling transduction pathways." (PMID 36439165, 2022). "Secondary endpoints defined as tumor tissue infiltration with CD4+, CD8+ T-cells and CD20+ B-cells, lymphocytic response measured through cytokine concentrations (e.g., NFα, IFN-γ, RANTES) and antibody response (e.g., IL-10, IL-6) in patients’ blood, prostate and skin biopsies were positive." (PMID 36428811, 2022). "Similarly, the INHBA+ macrophage subset co-expressed pro-tumorigenic molecules such as IL6, TGFβ, TIMP1, CCL20, CXCL1, and IL10, highlighting the highly plastic and complex nature of tumor-infiltrating myeloid cells in vivo, consistent with recent similar studies in other solid tumors." (PMID 36439171, 2022). "In one study that highlighted this immune-regulation potential, Glycyrrhiza polysaccharide was fed to CT-26 tumor-bearing mice and significantly inhibited tumor growth, increased the immune organ index, activated CD4+ and CD8+ immune cells, and increased levels of IL-2, IL-6, and IL-7 cytokines." (PMID 36090181, 2022). "IL‐6 levels did not exhibit any changes in HCT116 tumours following the treatments." (PMID 35701366, 2022). "Studies have shown that activated MCs can recruit tumour-infiltrating effector T cells and natural killer cells by secreting CXCL10 and CXCL8, respectively; in addition, mast cells can also greatly alter B cell generation, development, and function by secreting cytokines such as IL-6." (PMID 35610596, 2022).
tumor (continued). "MiR-26 has been proven to be a multiple tumour suppressor; it does not control IL-6-related inflammation and tumour promoting activity through transcription inhibition but downregulates the production of IL-6 through HMGA1 and MALT1 silencing-induced NF-κB inhibition." (PMID 35864955, 2022). "Increased secretion of IL-6, TNFα, CCL2, CCL5, CXCL9 and GM-CSF, which are pro-inflammatory factors combined with decreased secretion of anti-inflammatory factors including IL-4, IL-28A, CCL24, CXCL12 and SCF from infected HEL299 fibroblasts, is expected to be tumor-promoting and enhance metastasis." (PMID 34575976, 2021). "Inhibition of trans-signaling may also have the added benefit of negating IL-6 responses in tumor cells that do not express CD126." (PMID 33414408, 2021). "To date, only one study has highlighted the effects of PDA tumor cells derived-EVs on MCs, resulting in their activation via EV-cell membrane receptor-mediated activation of ERK-1,2 signaling, leading to the upregulation of tissue-remodeling genes and the secretion of IL-6, IL-8, and VEGF." (PMID 34207163, 2021). "However, overexpression of IL6 in iBMSC obviously alleviated the tumor suppression effect of LPC, which is manifested by the acceleration of tumor growth, the improvement of ki67 + cells and the up-regulation of pERK1/2 and pSTAT3 levels in tumor tissues." (PMID 34790130, 2021). "In addition, previous studies have demonstrated that IL-6 together with the JAK/STAT3 signaling pathway in the TME participate in processes that strongly suppress immune effector cell function and facilitate tumor progression induced by CAFs." (PMID 34635121, 2021). "Therefore, in the triple cross-talk between tumor cells, CAF, and TAM, IL-6 and GM-CSF could become important targets for modulating their interaction." (PMID 34094963, 2021). "Indeed, at the bone metastatic site, IL-6 indirectly contributes to OC differentiation and activation by increasing RANKL expression in OB via the JAK/STAT-3 signaling pathway, thereby further promoting tumor local aggressiveness." (PMID 34124067, 2021). "We could not detect any differences in either examined interleukin (IL-6 and IL-8) between the patients with different tumor stages." (PMID 34440475, 2021). "However, it has been recently reported that tumor-derived Upd2 (the fly homologue of interleukin-6 (IL-6)) induces non-cell-autonomous autophagy around tumor tissues in the Drosophila cancer model of scrib/RasV12 eye imaginal discs." (PMID 34831432, 2021). "Inflamed VAT is a major contributor to the progression of systemic inflammation by secreting numerous pro-inflammatory cytokines including IL-1β, IL-6, and TNF-α into systemic circulation, which could have a remote effect leading to an increase in tumor aggressiveness." (PMID 35010352, 2021). "Vasculogenic mimicry is often observed in the hypoxic tumor microenvironment and is characterized by an increase in HIF-1α/MMP-9/VEGF signaling, the activation of epithelial-mesenchymal transition (EMT)-related proteins such as Twist1, and an upregulation of proinflammatory molecules such as IL-6." (PMID 34359588, 2021). "Previous research with an experimental model showed that tumour factors, such as proteolysis-inducing factor (PIF), and pro-inflammatory cytokines, such as IL-6 and TNF-α, could jeopardise the placenta tissue, impairing the connection between the dams and foetus." (PMID 33916290, 2021). "Macrophages represent key players in anti-tumor immunity through phagocytosis and antigen presentation, which also actively participate in the production and regulation of immune effector cells, as well as secretion of cytokines (e.g., TNF-α, IL-1, IL-6, and interferon (IFN)-α/β)." (PMID 34845974, 2021).
tumor (continued). "A prospective exploratory study evaluating multiple cytokines has shown that a cutoff value of 6.53 pg/mL for IL6 and 60.8 pg/mL for IL8 was associated with overall survival irrespective of tumor entity after 90Y radioembolization (RE) in patients with HCC or metastatic disease." (PMID 34080071, 2021). "IL-6 is shown to inhibit the expression of tumor suppressors, notably BIM and PTEN, and this may contribute to advancing MYC-driven B cell tumorigenesis." (PMID 33651821, 2021). "Notably, combination therapy with ICIs and anti-IL-6 antibody did not synergistically extended survival or reduced tumor growth, compared with single agent treatment." (PMID 34103524, 2021). "Indeed, fat from KPC tumor mice had the lowest mean Ct for Il6, and skeletal muscle from KPC tumor mice had the lowest mean Ct for Il6r, implicating fat and muscle as the predominant sources of Il6 and Il6r in our model, respectively." (PMID 33851955, 2021). "Likewise, in the present study, IL-6, a driving causation of CRS, was not produced by AdCAR NK-92 cells after co-incubation with either tumor cell line or a specific bAb." (PMID 33807875, 2021). "Moreover, the additional anti-tumor mechanism of tramadol was confirmed in vivo by preserving NK cell activity to maintain immune function and decrease the production of pro-inflammatory cytokines such as TNF-α and IL-6." (PMID 34764420, 2021). "In contrast, M2-like cells not only produce tumor growth factors such as IL-6 but also produce angiogenic molecules, including VEGF and immunosuppressive factors such as arginase 1 (Arg1), IL-10, TGF-β, and indoleamine 2,3-dioxygenase (IDO), resulting in tumor promotion." (PMID 34071550, 2021). "Conversely, while in the pivotal cohort IL-6 emerged as a differentially expressed antigen (PCa versus HD), in the training cohort the levels of IL-6 showed a modest, not significant trend of correlation with increasing pathological Tumor-Node-Metastasis (pTNM) staging." (PMID 34155195, 2021). "Therefore, this study aimed to evaluate IL6 dysregulation in ESCC and to identify potential targets that could contribute to tumor phenotypes." (PMID 34422669, 2021). "Furthermore, various secretions (TGF-beta, vascular endothelial growth factor (VEGF), IL-6, IL-10, prostaglandin E2 (PGE2), and chemokines) by the M2 macrophages act to promote tumour metastasis and Treg expansion with concomitant suppression of effector T cell activity." (PMID 34202255, 2021). "However, the activity of DCs to induce anti-tumor responses is suppressed by TME dampening of DC maturation, differentiation, or cell migration, with numerous TME effector molecules (e.g., IL-6, IL-10, VEGF, TGF-β, CSF-1) involved in suppression of DC activities." (PMID 35002732, 2021). "In conclusion, the data presented in this review, obtained from in vitro and in vivo experiments and from clinical samples, strongly supports the role of IL-6 and OSM on EMP promotion and suggests that both cytokines could be potential therapeutic targets to halt tumour progression by blocking EMP." (PMID 34361105, 2021). "The secreted factors include interleukin (IL)-1, IL-6, IL-8, tumor necrosis factor-alpha (TNF-α), hepatocyte growth factor (HGF) and vascular endothelial growth factor (VEGF), which in turn promote not only tumor growth but also cancer metastasis in the tumor microenvironment." (PMID 35111685, 2021). "Given that tumor cells constantly interact with multiple cytokines simultaneously present in the TME, inducing a complex web of cross-talk between different pathways induced by each cytokine, we were interested to understand the effect of simultaneous administration of IL-6 and TGF-β in Huh-7 cells." (PMID 35127527, 2021).